CNN2P12 (calponin 2 pseudogene 12)
Gene: Processed pseudogene on chromosome 13 (18,726,706 to 18,727,414, forward strand). Ensembl gene ENSG00000204718.
Diseases named in the same sentence as CNN2P12 in open-access papers:
CNN2P12 is named in the same sentence as 1 disease in open-access papers, as found by Europe PMC text mining. Sharing a sentence is not in itself a finding about the gene and the disease.
CNN2P12 shares sentences with these, for which no sentence is quoted: tumor (1 paper).